SPARC (secreted protein acidic and cysteine rich)
Diseases named in the same sentence as SPARC in open-access papers (continued):
Sharing a sentence is not in itself a finding about the gene and the disease.
tumor (continued). "In addition, the tumor endothelium expresses 2 albumin-binding proteins, namely, secreted protein acidic and rich in cysteine (SPARC) and gp60 receptor, which may facilitate the uptake and retention of the HSA complex in the tumor interstitium." (PMID 27564255, 2016). "In addition, the inflammatory TME in low/absence of SPARC can contribute to immune suppression enabling tumor cells to evade the immune system and disseminate." (PMID 27564266, 2016). "This is an important observation since the malignant epithelial component of the tumor transplants generated from the SPARC-transfected As+3-and Cd+2-transformed cell lines showed a low level of expression of SPARC mRNA and no expression of the SPARC protein by western blotting." (PMID 26783756, 2016). "Finally, as nab-paclitaxel is thought to act by binding SPARC in the tumour microenvironment, increasing its local concentration, it is possible that the absence of SPARC near single cells spares them from cytotoxicity." (PMID 27628423, 2016). "They concluded that the prognosis was worse when the tumor showed negative SPARC immunostaining." (PMID 27421134, 2016). "This conclusion could be showed in subgroup analyses, especially in the subgroup of cell type, which showed that high SPARC expression in the stroma, but not in the tumor, was a strong prognostic indicator of lower OS." (PMID 26731428, 2016). "The absence of expression of SPARC in the superficial component of the tumor might also suggest that a significant increase in expression is mainly observed in tumor stages more locally advanced." (PMID 24396828, 2013). "Thus, SPARC and SLUG expression is required for tumor invasion in 3-dimensional cultures." (PMID 22911700, 2012). "TGFβ1 contributes to many aspects of tumor development including metastasis, endothelial cell permeability, inflammation and fibrosis, all of which are altered in the absence of stromal-derived SPARC." (PMID 22348081, 2012). "In addition, the extent of SPARC and pAKT suppression by HSP27 depletion is likely influenced by other factors that can independently regulate pAKT, such as the genetic background of the tumor cells with respect to PTEN status." (PMID 22480225, 2012). "Therefore, the final effect is that SPARC expression itself does not alter the overall tumor cell survival." (PMID 22480225, 2012). "However, targeting SPARC alone is not a good therapeutic approach as tumor cell survival is increased." (PMID 22480225, 2012). "Therefore, losartan effectively reduced the expression, activation and signaling of TGFβ1 during tumor progression in the absence of host SPARC." (PMID 22348081, 2012). "However, despite neither siRNA treatment resulting in the loss of this signaling, inhibition of this pathway did not have a big impact on tumor cell survival, also supporting the conclusion that SPARC is not a strong chemosensitizer." (PMID 22480225, 2012). "SPARC may be potentially anti-tumorigenic through the induction of a microenvironment that is non-permissive to tumour progression." (PMID 21818290, 2011). "However, the primary tumor growth rates (in vivo growth) of SPARC expressing MDA-MB-231 cells were not studied." (PMID 18328103, 2008). "Angiogenesis-related genes (FLT1, KDR, SPARC, INSR, ANGPT2, and FLT4) and MHC-I molecules (HLA-A, HLA-B, HLA-C, HLA-E, and HLA-F) were highly expressed in cluster 3 ECs, indicating that the cells may function as antigen-presenting cells and promote tumor parenchymal angiogenesis." (PMID 37533434, 2023). "Albumin was originally thought to bind to SPARC (secreted protein acidic and rich in cysteine) in the tumor microenvironment, however more recent experimental data revealed that increased delivery and antitumor activity of nab-paclitaxel does not depend on the interaction with SPARC." (PMID 34282781, 2021).
tumor (continued). "Therefore, SPARC may also play an important role in regulation of the interaction between collagen deposition and leukocyte recruitment to drive the induction of EMT in tumor microenvironment." (PMID 32900381, 2020). "Likewise, in our in vivo model, the finding suggested that if the in vivo levels of SPARC are low, the expression of MMP-2/9 and p-ERK would be downregulated to suppress the formation and development of ectopic HCC cell tumor, thereby inhibiting the proliferation of the tumor." (PMID 32670867, 2020). "According to studies, increased expression of SPARC might lead to activation and subsequent phosphorylation of ERK1/2, with p-ERK regulating the transcription of MMP-2/9, thus promoting cell growth and proteolysis of extracellular matrix related to tumor invasion." (PMID 32670867, 2020). "However, their increased phosphorylation in absence of stromal-Sparc suggests either they augmented the stimulation due to increased energy demands or minimal or there is no implication in the tumor suppressor effect of SPARC in the model system reported herein." (PMID 30332737, 2018). "IHC analysis on type 1 EC showed that the selected adipokines are differently expressed within the tumor; staining could be located in the cytoplasm of EC cells (TNF α and RBP4), in the cytoplasm of stromal cells (adiponectin) or both in EC and stromal cells (IL-6 and SPARC)." (PMID 28505082, 2017). "Furthermore, SPARC (secreted protein acidic and rich in cysteine), which is widely present in the extracellular matrix (ECM) of tumor tissue, can attract nanoparticles to inner tumor areas, thus resulting in increased anti-tumor activity, such as Abraxane (paclitaxel-loaded HSA nanoparticles)." (PMID 27086917, 2016). "Since stabilin-1 mediated uptake of such ligands may limit their availability in the tumor microenvironment we have examined whether clearance function is affected in stabilin-1 ko TAM using common stabilin-1 ligand acetylated low density lipoprotein (acLDL) and protein ligand SPARC." (PMID 27105498, 2016). "As SPARC can potentially promote AKT survival signaling through ILK and/or HSP27, we hypothesized that HSP27 may serve as a downstream target, not only to inhibit SPARC-induced migration and invasion, but also to eliminate SPARC-induced tumor cell survival signaling through AKT activation." (PMID 22480225, 2012). "Therefore, it is tempting to speculate that targeting these matricellular proteins (e.g., SPARC, ANGPTL4, and hdOPN) would either increase the infiltration of immune cells to inhibit tumor growth or induce apoptosis by stripping off their anoikis survival capabilities." (PMID 22481923, 2012). "However, the role of SPARC on tumour cell-induced angiogenesis has not been clearly established." (PMID 20087345, 2010). "SPARC expression was found in tumor and stromal cells but not in the adjacent normal oral mucosa in HNSCC40 and correlated with better tumor response to nab-paclitaxel in HNSCC patients." (PMID 38467604, 2024). "The most enriched glycoproteins in tumour ECM compared to non-tumour ECM included thrombospondin-2 (16.9-fold), MXRA5 (14.4-fold), peroxidasin (2.5-fold), thrombospondin-1 (2.5-fold), SPARC (2.3-fold), FRAS1 (2.3-fold) and tenascin-C (2.1-fold)." (PMID 37397358, 2023). "TIL density, PD‐L1 expression in tumor cells and PD‐1 expression in TILs were not significantly different between patients with SPARC+ and SPARC− CAFs." (PMID 36346290, 2023). "Third, although there is a link between SPARC expression and tumor stage, the TNM (tumor node metastasis) staging system was not used in any of the eligible studies." (PMID 35981080, 2022). "This fits with our finding that SPARC expression was upregulated by JBS2 in the intraductal model, potentially exerting a negative effect on tumor cell migration/invasion." (PMID 35267611, 2022).
tumor (continued). "Histopathology of the tumors and expression of tumor markers CD99, SPARC, and MyoD1 did not change significantly upon successive mouse‐to‐mouse passaging in 12 PDX models studied by IHC." (PMID 33837665, 2021). "Using conventional whole biopsy sequencing, SPARC and COLIA1 were identified as metastatic markers, but were not significant in the primary tumour." (PMID 31959771, 2020). "Other factors that drive macrophage-mediated tumor invasion include Wnt5a, which acts through the non-canonical WNT pathway to stimulate cancer cell motility, and SPARC/Osteonectin, which regulates the deposition of collagen fibers and expression of MMPs." (PMID 29594035, 2018). "Although stabilin-1 ligands such as SPARC are known to modulate tumor progression the role of endocytic clearance function of stabilin-1 in TAM and its relation to tumor growth was not studied before." (PMID 27105498, 2016). "Profiling with immunohistochemistry and PCR-based panels revealed the tumor to be positive for TL3, a member of the transducing-like enhancer of split (TLE), negative for monoclonal and polyclonal SPARC." (PMID 25126591, 2014). "For HF373 tumor cells, HSP27 inhibition did not suppress SPARC or pAKT, suggesting that in this primary cell line, SPARC expression was not under control of HSP27." (PMID 22480225, 2012). "In HF2303 tumor cells, inhibition of HSP27 did decrease SPARC expression by 50%, but the decrease in both SPARC and HSP27 was not sufficient to decrease pAKT levels, suggesting additional pathways independently governing pAKT expression in these cells." (PMID 22480225, 2012). "The mean SPARC and FOXP3 expression in the primary tumours of patients with and without disease recurrence at each time point were measured to determine if the levels correlated with disease recurrence over time." (PMID 21818290, 2011). "Moreover, analysis of paired tumor and normal tissue samples showed no significant differential expression of COL1A1, PDGFRB, and SPARC." (PMID 41040657, 2025). "However, SPARC expression in TNBC has never been correlated with clinicopathological parameters, such as age, histopathologic grade, tumor size and lymph node metastasis." (PMID 36346290, 2023). "Furthermore, the transplantation route did not influence the expression of α-SMA, SPARC and FAP, but we found a higher ratio of collagen I in orthotopic PDX models and a decrease in corresponding tumor cells." (PMID 38136299, 2023). "Although SPARC may increase the PTX concentration in tumor cells (tissue including the microenvironment), our data demonstrated that high SPARC expression in tumor cells did not enhance the effectiveness of nab-PTX." (PMID 28050738, 2017). "Additionally, in contrast to the low levels found in the non-transfected urosphere (TIC) tumor transplants, the SPARC-transfected urosphere (TIC) tumor transplants had increased levels of SPARC in 3 of the 4 TIC tumors." (PMID 26783756, 2016). "However, if SPARC expression is independent of HSP27, pAKT will be high despite the inhibition of HSP27, and the tumor cells will survive better in TMZ." (PMID 22480225, 2012). "Other studies have shown that SPARC interferes with the growth promoting effects of VEGF on endothelial cells, and promotes the assembly of tightly organized stroma that does not permit blood vessel formation or tumor progression." (PMID 20671917, 2010). "The correlation between osteomimicry and tumor purity was then investigated, and result showed that SPARC and SPP1 expression had a moderate-to-strong and positive correlation with tumor purity, while BGLAP expression had a poor-to-moderate and negative correlation with tumor purity." (PMID 33240930, 2020).
cancer (351 papers, 2003 to 2026). A tumor composed of atypical neoplastic, often pleomorphic cells that invade other tissues. "We recently identified 115 cancer-associated fibroblast genes (CAFGs) with high stromal specificity (stroma-to-epithelial ratio ≥10) and strong correlation with SPARC expression in CRC tissue (GSE35602)." (PMID 41228323, 2025). "On the other hand, the additional 5 genes showed a high R-index = 0.9 or beyond, and COL11A1 and TAGLN expressions as shown in red letters were uniquely associated with SPARC expression in cancer stroma of the TNBC tumors (both R-index below 0.6 in total BC)." (PMID 39335478, 2024). "The infiltration of cancer-associated fibroblasts (CAFs) was positively correlated with EMT gene SPARC expression, thus increasing the risk of poor survival of MESO." (PMID 37509139, 2023). "While expression of SPARC is often associated with promotion of metastases, cancer progression and poor prognosis, some studies suggest the opposite role for SPARC depending on the environment and progression/metastatic state." (PMID 36809527, 2023). "Analysis of the expression of the 85 secretome genes in > 12,000 tumors revealed that SPARC is a PanCancer indicator of cancer-associated fibroblasts’ infiltration." (PMID 36604669, 2023). "SPARC overexpression has been identified as a risk factor for reduced recurrence-free survival of CAF-cancer patients." (PMID 37988189, 2023). "We found SPARC as a main PanCancer secretory protein linked with the presence of cancer-associated fibroblasts (CAFs) in multiple cancer types." (PMID 36604669, 2023). "Variants in the SPARC gene have been identified as susceptibility factors and as predictor and prognostic biomarkers in some cancers." (PMID 38137452, 2023). "As described in Cancer-Associated Mesothelial Cells Induce Chemotherapy Resistance above, SPARC expression in mesothelial cells caused an increase in TGF-βI secretion." (PMID 37545408, 2023). "In PC, there are several proteins such as the S100 family, a small integrin-binding ligand N-linked glycoprotein (SIBLING) family, and secreted protein acidic and rich in cysteine (SPARC) family proteins associated with cancer progression." (PMID 36498893, 2022). "SPARC, also termed osteonectin, was associated with brittle bone disorder with significance in metastasis and cancer invasion." (PMID 35571016, 2022). "In PCa and other types of cancer, secreted protein acidic and rich in cysteine (SPARC) has been associated with the induction of EMT-like features, such as E-cadherin loss and enhanced migration." (PMID 35682554, 2022). "This is consistent with other EMT pathway genes in the skin; COMP, CTHRC1, ECM2, FBN1, LOX, and SPARC were all upregulated in samples with a mutation in a cancer gene." (PMID 36531005, 2022). "SPARC is an extracellular matrix glycoprotein secreted by kinds of cells and has been shown to be associated with the cancer progression." (PMID 35912006, 2022). "Unexpectedly, cancer-associated fibroblasts expressed comparable levels of SPARC compared with fibroblasts from normal endometrium." (PMID 33579227, 2021). "The effects of SPARC in host tissues have been studied by transplantation of cancer cells into SPARC-deficient mice." (PMID 33579227, 2021). "Secreted protein acidic and rich in cysteine-like 1 (SPARCL1) belongs to the SPARC-associated family of matricellular proteins and is frequently found to be decreased in a number of cancer types." (PMID 33897765, 2021). "Particular interest among albumin binding proteins is attracted by SPARC, which is overexpressed in the extracellular matrix and in various cancer cells and is associated with tissue growth and cell proliferation." (PMID 32733871, 2020). "Together with our earlier reports that SPARC is required for stromal cell differentiation and acquisition of cancer-associated phenotype, we sought to determine the effect of SPARC on adipocyte differentiation and acquisition of CAA phenotype." (PMID 30765860, 2019).
cancer (continued). "The functions and disease association of SPARC in cancer is being increasingly appreciated as it plays multi-faceted contextual roles depending on the cancer type, cell of origin and the unique cancer milieu at both primary and metastatic sites." (PMID 27564266, 2016). "Adding exogenous SPARC to cell lines derived from these cancers inhibits cancer cell growth, suggesting that a loss of SPARC promotes tumorigenesis by facilitating cell proliferation." (PMID 26926673, 2016). "Overexpression of SPARC is also associated with many cancers and high expression in the cancer cells often increases metastatic potential." (PMID 26926673, 2016). "Suggesting an important and context-dependent relationship with cancer, both increased and decreased SPARC levels are associated with tumorigenesis." (PMID 26926673, 2016). "Our future plan is to perform some more cellular experiments to study the association between SPARC expression and chemo-sensitivity in various cancers." (PMID 28053291, 2016). "Secreted protein acidic and rich in cysteine (SPARC), a calcium-binding matricellular glycoprotein, is implicated in the progression of many cancers." (PMID 22879971, 2012). "Noteworthy, of all the 'digital' hits, the 2072 SPARC polymorphism had the clearest association with cancer." (PMID 17201911, 2007). "Aberrant SPARC expression has been implicated in cancer and fibrotic diseases." (PMID 41018070, 2025). "Screening of aggressive cancer-associated DEGs and important pathways revealed that SPARC could be a promising target gene in metastatic breast cancer." (PMID 37577749, 2023). "Notably several of these proteins and proteoglycans, including collagens, SPARC, biglycan, and tenascin-C, are associated with angiogenesis and metastatic progression in many cancer types." (PMID 36505823, 2022). "Of note, the association between the serum SPARC and prognosis might be conflicting in patients with different cancer types." (PMID 34912848, 2021). "Before the analyses, the hypothesis was that physical activity suppresses cancer growth by increasing serum SPARC levels, and thus higher SPARC levels may be associated with a reduced relapse rate and longer RFS." (PMID 32512862, 2020). "SPARC suppressed metabolic programming of both adipocytes and OvCa cells and exerted an inhibitory effect of adipocyte differentiation and their phenotypic switch to cancer-associated phenotype." (PMID 30765860, 2019). "Our findings that phenformin mitigated the increased tumor burden of syngeneic tumors in Sparc-deficient mice suggest that the tumor suppressor effect of SPARC in OvCa is mediated, in part, through metabolic programing of cancer cells targeting the mitochondrial ETC." (PMID 30332737, 2018). "Secreted Protein Acidic and Rich in Cysteine (SPARC/osteonectin) is an extracellular matrix-associated glycoprotein involved in the regulation of cell proliferation and cell migration in several types of cancers." (PMID 28969021, 2017). "Thus, reduced expression of SPARC is associated with poor prognosis and aggressive clinicopathological features in both cancer cells and MSC." (PMID 26731428, 2016). "Statistical elaboration related to stromal SPARC expression was significantly associated with habitual smokers and consumers of alcohol, highlighting how these habits can be, once again, poor prognostic factors for this cancer." (PMID 24396828, 2013). "Another interesting association with cancer can be observed in the SOX-5/miR-29a/SPARC circuit." (PMID 20731828, 2010). "SPARC overexpression by the malignant cells themselves or by neighbor fibroblasts and endothelial cells has been associated with poor prognosis in different human cancer types." (PMID 19337591, 2009). "Therefore, we hypothesized that high physical activity suppresses cancer growth by raising serum SPARC levels, and thus higher SPARC levels may be associated with a lower relapse rate and longer relapse-free survival (RFS)." (PMID 32512862, 2020).